NLRP3 (NLR family pyrin domain containing 3)
Diseases named in the same sentence as NLRP3 in open-access papers (continued):
Sharing a sentence is not in itself a finding about the gene and the disease.
infection (continued). "NLRP3 inflammasome is a molecular complex that triggers innate immune defense through the maturation of pro-inflammatory cytokines such as interleukin-1beta (IL-1beta) in response to danger signals, such as from infection and metabolic disorders." (PMID 35627209, 2022). "Furthermore, infection of PCV2 and PRV caused inflammasome proteins NLRP3 and COX2-mediated cellular inflammatory reaction, and the coinfection of PCV2 and PRV aggravated the inflammation." (PMID 35457287, 2022). "Interestingly, cytochalasin D also abolished the weaker inflammasome-independent, T6SS3-dependent cell death observed upon infection of Nlrp3-/- BMDMs." (PMID 36155655, 2022). "Caspase-1−/− and Asc−/− BMDMs in contrast showed significantly reduced IL-1β levels upon infection, indicating that NLRP3 inflammasome components (ASC) and targets (caspase-1) function upstream of GSDMD and have a potential dual role in cell death and release of pro-inflammatory cytokines." (PMID 34718331, 2021). "In Plasmodium berghei and Aspergillus fumigatus, AIM2 and NLRP3 may function in a redundant manner to trigger inflammasome activation and, consequently, aid in pathogen infection control." (PMID 33897690, 2021). "Vaccinia virus (VACV) infection induces NLRP3-independent maturation of caspase-1." (PMID 34638790, 2021). "This suggests that both DDX3X and G3BP1 are required for IAV–ΔNS1–induced SGs and led us to hypothesize that disrupting expression of Ddx3x or G3bp1 might restore NLRP3 activation after IAV–ΔNS1 infection." (PMID 33766561, 2021). "Finally, to address the role of lysosomal cathepsin B in regulating the activation of NLRP3 inflammasome during ΔpknF mutant infection, release of cathepsin B was measured at 0, 2, 4, 6, 20 and 24 hpi." (PMID 34324582, 2021). "In the context of infection, the T3SS effector Salmonella invasion protein B (SipB) from S. typhimurium, localizes to mitochondria causing their swelling and depolarization, which subsequently induces oxidized mtDNA-mediated NLRP3 inflammasome." (PMID 34201509, 2021). "For example, IL-1β, which is induced by NLRP3 inflammasome activation to protect the host in the early phase of a viral infection, can also have serious negative consequences if the excessive production persists throughout the infection." (PMID 34150848, 2021). "Moreover, inflammation, due to infections, is driven by the NLRP3 activation through PAMPs and DAMPs." (PMID 34209586, 2021). "Routinely, viruses are often identified post-infection by pattern recognition receptors (PRRs), such as the inflammasome sensor NLRP3, which trigger the production of interferons (IFNs) and inflammatory cytokines (e.g., IL-1, IL-6, and TNF) and initiate a local/systemic response to infection." (PMID 34572585, 2021). "Moreover, elevated levels of chemokines MIP-1β, KC, and RANTES observed in the lungs of Nlrp3−/− mice are responsible for attracting T-cells, dendritic cells, NK cells, and neutrophils to sites of infection." (PMID 34690967, 2021). "Thus, we conclude that secretion of IL-1β in response to GEVs infection in vitro is mediated by NLRP3 inflammasome and NLRP3 inflammasome plays vital roles in regulating inflammatory response." (PMID 33798196, 2021). "For example, in the context of lethal influenza A virus (IAV) infection, the NLRP3 inflammasome played a crucial role in virus clearance during early-stage infection, however it induced harmful inflammatory response that contributed to pathogenesis and mortality during late-stage infection." (PMID 34299310, 2021). "Also, MFN2 is required for NLRP3 activation after infection with RNA viruses, such as influenza, measles, or encephalomyocarditis virus (EMCV)." (PMID 34638790, 2021). "However, the reverse was true for mannose receptor 1, with significantly elevated transcript levels were observed in the wild type than Nlrp3−/− mice on day 7 post-infection." (PMID 34690967, 2021).
infection (continued). "On the opposite, LPS-primed U937 expressing NLRP3 S806A, D, or E mutants secreted IL-1β as WT U937 in response to infection by Salmonella enterica serovar Typhimurium (SL1344 strain) and transfection with poly(dA:dT), activating the NLRC4 and AIM2 inflammasomes respectively." (PMID 34615873, 2021). "In that study, the levels of serum IL-18 were also found to be increased in parallel with those of serum IL-10 in Lm-infected B6 mice at 72 h post-infection, whereas B6.Nlrp3−/− mice had significantly reduced serum IL-18, which indicated that NLRP3 expression is relevant for IL-18 production." (PMID 35053151, 2021). "Taken together, these results indicated that the NLRP3 pathway was activated during H2 infection and significantly involved in cell death and, especially, IL-1β release, however, the activation of NLRP3 accounted only partly for the overall cell death induced by H2." (PMID 34009097, 2021). "Type I IFNs and the NLRP3 inflammasome responses are also key for activating adaptive immune responses, which play an essential role in controlling viral titers in later stages of infection and also subsequent IAV infections." (PMID 33766561, 2021). "Indeed, the aberrant activation of NLRP3 and downstream mediators often lead to pathological tissue injury during infection." (PMID 34209586, 2021). "NLRP3, activated by multiple Influenza PAMPs, results in the formation of the NLRP3 inflammasome and the production of pro-inflammatory cytokines that recruit leukocytes (macrophages, lymphocytes, granulocytes, etc.)to the lungs during infection." (PMID 34959590, 2021). "The results thus far demonstrated that Nlrp3−/− macrophages clear bacteria more efficiently than their wild-type counterparts and that the levels of pro-inflammatory cytokines are higher in both Nlrp3−/− macrophages and mice following infection with F. tularensis LVS." (PMID 34690967, 2021). "NLRP3 activation and caspase-1-dependent pyroptosis occurs also after infection with the HCV." (PMID 34201847, 2021). "Upon infection, ASC dissociates from both IRGM and the Golgi and associates with HCV-induced NLRP3." (PMID 33208442, 2021). "Similarly, the involvement of NLRP3 inflammasome can also be observed in various CNS diseases such as infection, ischemia, and degeneration." (PMID 33928044, 2021). "To test whether the reduced NLRP3 inflammasome activation was due to the increased production of IFN-β that occurs after IAV–ΔNS1 infection, we analyzed the effect of IFN-β supplementation on NLRP3 inflammasome activation in response to IAV infection." (PMID 33766561, 2021). "However, IL-18 response requires both Aim2 and Nlrp3 following F. tularensis LVS as well as F. tularensis SchuS4 infections." (PMID 34690967, 2021). "The NLRP3-inflammasome is initially generated to restore cellular homeostasis and to avoid infections or situations in which damage may occur." (PMID 34829842, 2021). "NLRP3 is crucial in the host’s innate immune response, especially in combating pathogen infections; however, excessive NLRP3 activation in response to extensive tissue damage, such as that observed in patients receiving HSCT, plays a critical role in the development of transplant complications." (PMID 34769275, 2021). "At a higher infection dose of 1×104 CFUs, all wild-type mice succumbed to infection by day 9 post-infection; however, 25% (2/8) of the Nlrp3−/− mice survived this infection dose with an enhanced median survival time (MST) of 13days compared to 9days for the wild-type mice." (PMID 34690967, 2021). "NLRP3 dependent pathology was independent of infection duration but strongly associated with higher early infectious loads." (PMID 34526512, 2021). "Consequently, TMEV infection induces strong NLRP3 inflammasome and downstream prostaglandin E2 (PGE2) signaling in dendritic cells (DCs) and macrophages/microglia from susceptible SJL mice compared to the cells from resistant B6 mice." (PMID 34067536, 2021).
infection (continued). "Overall, our study provides preliminary data to suggest that the Sars-Cov-2 E protein suppresses NLRP3 inflammasome activation during the early stages of infection while in the later stages it may enhance NLRP3 inflammasome activation." (PMID 34952919, 2021). "NLRP3-/- mice expressed higher levels of IL-1β than WT at day 3 post-infection." (PMID 33524073, 2021). "However, comparison between the antifungal effects of IFN-γ and NLRP3 needs to use the infection model with the same mouse background and infection dose." (PMID 34912336, 2021). "Second, we cannot exclude the possibility that the non-AIM2-dependent signaling pathway may be induced to compensate for the impaired autophagy flux, such as the NLRC4-dependent way in infection-induced autophagy or the NLRP3 inflammasome–autophagy crosstalk." (PMID 34740380, 2021). "In addition, IL-1β production in murine dendritic cells and macrophages after infection with encephalomyocarditis virus (EMCV) or vesicular stomatitis virus (VSV) is dependent on NLRP3 inflammasome." (PMID 34201847, 2021). "However, the levels of p-IκB were significantly higher in the Nlrp3−/− than those in the wild-type macrophages 2 and 3h post-infection." (PMID 34690967, 2021). "Infection of bMECs with Prototheca spp., especially P. bovis, damaged mitochondria and promoted mtROS accumulation, which activated an inflammatory response through the NF-κB and NLRP3 inflammasome pathways and enhanced IL-1β production." (PMID 34895324, 2021). "However, after prolonged infection for 48 h, expression of NLRP3 and ASC increased more than 3-fold as compared with their respective basal levels." (PMID 35111047, 2021). "Elucidating the potential mechanisms of the coordinated mtROS generation could help develop further knowledge on host defense through appropriate activation of NLRP3 inflammasome complex during infections by various pathogens." (PMID 32922385, 2020). "We thus crossed Nlrc4−/− mice with Nlrp3- or Casp11-knockout animals to obtain Nlrc4−/−Nlrp3+/− and Nlrc4−/−Nlrp3−/− littermates, as well as Nlrc4−/−Casp11+/− and Nlrc4−/−Casp11−/− littermates, for infections." (PMID 31953493, 2020). "Furthermore, mRNA levels of factors activated by the NLRP3 inflammasome (IL-1β and IL-18) were significantly decreased in Gm28309 overexpressed cells, but higher in S2308 infection group, as well as protein secretion levels detected using ELISA." (PMID 33414782, 2020). "Inflammasomal response is critical for host defense against the infection, such that mice lacking NLRP3 or ASC are more susceptible to bacterial infection." (PMID 32751530, 2020). "In addition, various danger signals unrelated to infection can trigger the NLRP3 inflammasome, including ROS, Ca2+, nitric oxide (NO), and mitochondrial dysfunction (MtD)." (PMID 32148650, 2020). "Thus, NLRP3 deficiency mice are more susceptibility to HSV-1 infection and exhibit early onset of death upon the infection." (PMID 32187211, 2020). "An experimental study in a murine model infected with L. amazonensis, L. braziliensis, and L. infantum chagasi showed that IL-1β production derived from the activation of the NLRP3 inflammasome led to host resistance to infection by the production of nitric oxide (NO)." (PMID 33192178, 2020). "Interestingly, NLRC4 S533A interacts directly with infection-induced NLRP3, which further recruits ASC and activates caspase-1181." (PMID 32550001, 2020). "Furthermore, NLRP3 expression increased after 6 h of infection with H. pylori, but downregulated at a later period." (PMID 32230726, 2020). "However, host factors upstream or downstream of NLRP3 inflammasome also play a crucial role in colonization and infection processes." (PMID 33424869, 2020). "Infection, tissue lesions and oxidative stress can activate the NLRP3 inflammasome." (PMID 33614540, 2020). "However, dysregulation of NLRP3 inflammasome activation can lead to pathological responses during infection." (PMID 32630319, 2020).
infection (continued). "Although, innate immune mechanisms such as optimal activation of the NLRP3 inflammasome plays an important role in antiviral host defenses, its aberrant activation and downstream mediators often lead to pathological tissue injury during infection." (PMID 32574259, 2020). "A key immune pathway that responds to infection is orchestrated by the NLRP3 inflammasome." (PMID 32750090, 2020). "This genetic approach was not only useful for supporting the previously published association of the NLRP3 rs10754558 variant with Mtb infection, but also for revealing that NLRC4 could be another genetic factor important for the outcome of infection." (PMID 33193317, 2020). "The expression of NLRP3 increased with time in DF1 cells after GM infection." (PMID 32293543, 2020). "Here, we determined whether CASP-1 activation (an essential component of the NLRP3 inflammasome) participates in infection control mediated by eUTP." (PMID 33061823, 2020). "Indeed, a HAdV-5 infection of the PMA differentiated macrophage-like THP-1 cell line resulted in an inhibition of the NLRP3 inflammasome." (PMID 33086737, 2020). "The appropriate activation of the NLRP3 inflammasome and pyroptotic cell death are required for the induction of the innate and adaptive immune responses and antimicrobial host defense against a variety of infections." (PMID 32630319, 2020). "Thus, the profound NLRP3 inflammasome activation depending on the severity of the infection proves harmful to the host." (PMID 32849610, 2020). "It remains to be investigated whether activation of NLRP3 inflammasome-mediated cell death benefits the pathogen or the host during infection." (PMID 32013758, 2020). "Thus, we subsequently replicated MDM infection with Mtb H37Rv to confirm NLRP3 participation in inflammasome responses." (PMID 33193317, 2020). "The NLRP3 inflammasome plays pivotal roles in infection and inflammation and its activation may be mediated by P2X7Rs15." (PMID 32286307, 2020). "In addition, the NLRP3/caspase-1/IL-1β pathway plays an important role in leukocyte aggregation and fighting infection during Aspergillus fumigatus infection." (PMID 32148650, 2020). "Upon E. coli challenge, the Nlrp3 mRNA expression was upregulated at 3, 6 and 9 h post-infection in PMECs compared with untreated control cells (p < 0.001), but this increase was attenuated by L. johnsonii L531 pretreatment (p < 0.001, p < 0.001, and p = 0.038, respectively)." (PMID 32823867, 2020). "Indeed, H37Rv and isolate 411 released 52% and 37% less IL-1β upon infection of Nlrp3−/− cells as compared to wildtype iBMDMs." (PMID 32111888, 2020). "Therapeutic targeting of NLRP3 from day 1 with the potent NLRP3 inhibitor MCC950 also confirmed the requirement of inflammation to combat early disease, as mice were rendered more susceptible to HKx31 (H3N2) and PR8 infection by MCC950 treatment." (PMID 32260457, 2020). "We speculate that neutrophils that arrive at the site of infection have an initiated priming of the NLRP3 inflammasome and serine proteases due to chemotactic gradient migration." (PMID 33318544, 2020). "However, NLRP3-independent routes to IL-1β release have been reported in mouse infection models, leaving the role for NLRP3 in vivo less clear." (PMID 32385301, 2020). "Interestingly, it has been demonstrated that VZV induces the formation of an inflammasome through the NLR, NLRP3, leading to secretion of pro-inflammatory IL-1β following infection of the monocytic THP-1 cell line." (PMID 32038653, 2020). "The NLRP3 inflammasome controls the maturation and secretion of the proinflammatory cytokines IL-1β and IL-18 and is important for the innate immunity against pathogen infection." (PMID 32582195, 2020). "The noncanonical pathway of NLRP3 activation is associated with the detection of intracellular LPS generated following infection by Gram-negative bacteria, such as Escherichia coli, Salmonella typhimurium, Shigella flexneri, and Burkholderia thailandensis." (PMID 31590215, 2019).
infection (continued). "Therefore, in a context of inefficient IFN response, viral replication-induced lytic cell death activates of the NLRP3 inflammasome to fight against infection." (PMID 31024004, 2019). "Moreover, this involvement occurs at an early stage of infection process because IL-1β levels were only decreased upon NLRP3 inhibitor treatment on day 1 post-infection." (PMID 30964929, 2019). "Although the activation of NLRP3 inflammasome is largely beneficial to the host defense during infections and metabolic processes, over production of IL-1β and IL-18 results in sterile inflammation, which can increase the risk of developing metabolic and autoinflammatory diseases among patients." (PMID 30873162, 2019). "Moreover, the germline NLRP3 knock-out mice infected with biofilm of clinical C. neoformans strain HS1101 displayed a more severe infection and inflammation in the lung, which is also true for Casp1 KO and ASC KO mice." (PMID 31333658, 2019). "Our results suggest that blocking NLRP3 on the day of infection may prove to be a promising direction in preventing SSLF." (PMID 30635040, 2019). "Of note, Nlrp3–/–mice showed reduced pain hypersensitivity at earlier time points upon infection but developed pain hypersensitivity similar to WT mice after 5 days of infection." (PMID 31479495, 2019). "However, Nlrp3−/− alveolar Mφs had a greater drop in gMFI for Ym1 following infection compared with WT alveolar Mφs." (PMID 31586037, 2019). "NLRP3 deficiency did not alter viral loads in the footpad, spleen or muscle of mice at 1 or 6 days post infection." (PMID 31479495, 2019). "As to the biological function of the NLRP3 inflammasome in the field of infection, it plays a crucial protective role against several pulmonary fungi which could cause aspergillosis and cryptococcosis." (PMID 31333658, 2019). "Lower IL‐1β and IL‐18 levels in RH‐CHIKV infection may lead to dampened NLRP3 pathways, resulting in reduced joint inflammation during acute phase of infection." (PMID 31015278, 2019). "These insights into the relationship between the NLRP3 inflammasome and the pathogenesis of EVs infection may ultimately inform the development of novel antiviral drugs." (PMID 30858838, 2019). "Notably, the activation of NLRP3 inflammasome significantly promoted the release of IL-1β in the supernatants of mouse kidneys at 7 days post-infection." (PMID 31474993, 2019). "These complexes sense and respond to pathogen infection or tissue injury, and one of the most extensively studied inflammasomes is the NLRP3 (nucleotide and oligomerization domain, leucine-rich repeat-containing protein family, pyrin-containing domain 3 receptor)." (PMID 31906173, 2019). "Importantly, our data with human macrophages and clinical samples from LRV+ and LRV− patients, together with L.g.+ and different Leishmania isolated from humans, demonstrate that LRV dampens NLRP3 activation to favor infection and pathogenesis." (PMID 31754185, 2019). "Indeed, they have proposed a role for RLRs in NLRP3 inflammasome activation after infection with RNA viruses." (PMID 31024004, 2019). "Thus, NLRP3 was mainly responsible for inflammasome activation induced by S. suis epidemic strain SC-19 infection." (PMID 31170267, 2019). "As GBPs are known to be involved in pyroptosis, and Tg infection of rodent macrophages causes pyroptosis via NLRP1 and NLRP3, we reasoned that human macrophages infected with Tg might also undergo pyroptosis." (PMID 31268602, 2019). "Further studies in a mouse model of OVA-AAI, accompanied by infection with Chlamydia muridarum or Haemofilus influenza, demonstrated an increased expression of NLRP3 in airway epithelial and infiltrating immune cells, as well as enhanced IL-1β and caspase-1 mRNA levels in the lungs of infected mice." (PMID 31590215, 2019).